FOXP3 (forkhead box P3)
Diseases named in the same sentence as FOXP3 in open-access papers (continued):
Sharing a sentence is not in itself a finding about the gene and the disease.
autoimmune disease (continued). "Mutations in the FOXP3 gene can lead to autoimmune diseases such as Immunodysregulation, polyendocrinopathy, enteropathy, and X-linked (IPEX) syndrome in humans, often resulting in death within the first 2 years of life and a scurfy like phenotype in Foxp3 mutant mice." (PMID 33614551, 2021). "Additionally, the metabolic sensor LKB1 acts through AMPK promoting OXPHOS over glycolysis, and its deletion on Tregs led to alterations in cellular metabolism and the development of autoimmune diseases associated with dampened FOXP3 expression." (PMID 32153577, 2020). "Mutations of Treg signature genes cause severe autoimmune diseases as seen in FOXP3 mutations." (PMID 32367041, 2020). "Mutation in the Foxp3 gene impairs Tregs development and function, which further causes immune dysregulation polyendocrinopathy and enteropathy X-linked syndrome along with other grievous autoimmune diseases." (PMID 33329608, 2020). "FoxP3 gene mutations in human and mouse can cause severe autoimmune diseases in multiple organs." (PMID 32621335, 2020). "Furthermore, “loss of function” mutations at the Foxp3 gene locus can lead to a Treg related autoimmune disease referred to as immune-dysregulation polyendocrinopathy enteropathy X-linked inheritance syndrome (IPEX)." (PMID 33519807, 2020). "Abnormalities of forkhead box P3 (FOXP3) are implicated in various autoimmune diseases." (PMID 30918515, 2019). "However, depletion of Treg cells due to a mutation of the gene for transcription factor FoxP3 can lead to serious autoimmune disorders." (PMID 30693029, 2019). "For example, mutations of the gene encoding the Treg-specific transcription factor FOXP3, impaired Treg cell development and caused a fatal multi-organ autoimmune disease called immune dysregulation, polyendocrinopathy, enteropathy, and X-linked (IPEX) syndrome." (PMID 31340499, 2019). "Deficiency of the Foxp3 gene abrogates self-tolerance and causes autoimmune disease." (PMID 29535721, 2018). "Different data indicate the relevant role of these CD4+Foxp3+ Treg cells in the pathogenesis of autoimmune diseases, including the congenital deficiency of Foxp3, which results in the IPEX syndrome (immune dysregulation, autoimmune polyendocrinopathy, and inflammatory enteropathy)." (PMID 30116758, 2018). "Polymorphisms of FOXP3 gene promoter may affect the function or quantity of Treg, resulting in various autoimmune diseases." (PMID 28298239, 2017). "These cells have a relevant role in autoimmune diseases, and their congenital deficiency (due to mutations in the FOXP3 gene) is associated with the IPEX syndrome, characterized by immune dysregulation, autoimmune polyendocrinopathy, and inflammatory enteropathy." (PMID 29038617, 2017). "Therefore, Foxp3 gene promoter polymorphisms were associated with various autoimmune diseases and CMV infection in pediatric allogeneic hematopoietic stem cell transplantation." (PMID 28298239, 2017). "Similarly, development of spontaneous autoimmune diseases is observed in people with mutations in the gene encoding FOXP3, resulting in a group of diseases described as immunodysregulation polyendocrinopathy enteropathy X-linked syndrome (IPEX)." (PMID 27942026, 2016). "Forkhead box P3 (FoxP3)-positive regulatory T cells (Tregs) play a pivotal role in the preservation of self-tolerance, and Treg dysfunction has been implicated in many autoimmune diseases." (PMID 27901054, 2016). "During periods of light starvation, phototherapy to increase FoxP3+ Treg cell development may be a particularly efficient method of influencing autoimmune disease risk and severity." (PMID 25852682, 2015). "Compelling evidence show that FOXP3-deficient mice develop autoimmune disease." (PMID 25338013, 2014). "Several reports elucidated that Treg plasticity or IFNγ-producing Foxp3 positive cells might be one of the causes of autoimmune diseases or immunological disorders." (PMID 25133199, 2014).
autoimmune disease (continued). "Foxp3 plays an essential role in the suppressive functions of Tregs, and Foxp3 deficiency causes multiorgan autoimmune diseases such as those observed in the scurfy mouse and in patients with immunodysregulation polyendocrinopathy enteropathy X-linked syndrome (IPEX)." (PMID 25133199, 2014). "Scurfy is an X-linked recessive severe murine autoimmune disease resulting from a Foxp3 mutant." (PMID 24521175, 2014). "Moreover, the disease mimicked the autoimmune disease seen in Scurfy mice that bear a loss-of-function mutation in the FoxP3 transcription factor, indicating impaired Treg function." (PMID 25477880, 2014). "Foxp3 plays an essential role in the suppressive function of Tregs, and Foxp3 deficiency causes a multi-organ autoimmune disease, which can be observed in the scurfy mouse and in patients with immunodysregulation polyendocrinopathy enteropathy X-linked syndrome (IPEX)." (PMID 24058613, 2013). "In the mouse, deficiency of the Foxp3 gene triggers a rapid fatal multi organ autoimmune disease." (PMID 22849659, 2012). "Dysfunction of FOXP3 is known to cause fatal autoimmune diseases, immunopathology, and allergy." (PMID 22536257, 2012). "Mutations of forkhead box p3 (FOXP3), the master gene for naturally occurring regulatory T cells (nTregs), are responsible for the impaired function of nTregs, resulting in an autoimmune disease known as the immune dysregulation, polyendocrinopathy, enteropathy, X-linked (IPEX) syndrome." (PMID 21400500, 2011). "In humans Treg also play an important role in the immune balance, as patients lacking functional Treg, due to loss-of-function mutations in the transcription factor FOXP3, suffer from severe generalized autoimmune disease; immune dysregulation, polyendocrinopathy, enteropathy, X-linked (IPEX)." (PMID 19779623, 2009). "Interestingly, the majority of the genetic mutations associated with IPEX, a severe autoimmune disorder caused by functional inactivation of Foxp3, map to the carboxyl-terminal FKH domain or the leucine zipper domain in the central region of the protein." (PMID 16652169, 2006). "Notably, deletion of Cd74 substantially reduces peptide diversity of MHC class II molecules, impairs the elimination of autoreactive T cells in the thymus, and causes defects in Treg development by downregulating Foxp3, ultimately promoting autoimmune diseases." (PMID 41596668, 2026). "Contrary to adult mice, Foxp3 degradation in neonates led to severe autoimmune disease featuring pronounced T cell activation, myeloproliferation, and tissue inflammation similar to those in Foxp3-deficient Foxp3GFPKO mice indicative of a loss of Treg function." (PMID 40470210, 2025). "Mutations in the Foxp3 gene could potentially lead to a decrease in Treg cell function as well as the secretion of inhibitory cytokines, leading to a disruption in the immune homeostasis and the development of serious autoimmune diseases." (PMID 39935826, 2025). "On the other hand, estrogen has been shown to promote the amplification and immunosuppressive capacity of Tregs, which may be associated with the estrogen-induced upregulation of Foxp3 and PD-1, conferring protection against the development of experimental autoimmune disease models." (PMID 38659456, 2024). "Findings in other studies, together with the Foxp3-polymorphism-associated genetic effect on the risk of SLE identified in this study, confirm our hypothesis that Foxp3 polymorphisms might be a proper candidate for use in autoimmune disease screening, including for SLE." (PMID 37998578, 2023). "Differentiation, proliferation and maintenance of Tregs depend on the transcription factor Foxp3 and mutations leading to altered expression or function of Foxp3 may lead to a severe autoimmune disease called immunodysregulation polyendocrinopathy enteropathy X-linked syndrome." (PMID 35956047, 2022).
autoimmune disease (continued). "Tregs play important protective roles in limiting autoimmune disorders, but functional Tregs are susceptible to both epigenetic alteration of the usually-expressed FOXP3 gene and impaired estrogen signaling, which may impair immunity and increase susceptibility to autoimmune diseases." (PMID 36506464, 2022). "Hence, by decoding the regulatory network of FOXP3, and mapping the genetic risk to the key functional genes it impacts, we will gain a better understanding of how autoimmune diseases like T1D could be countered." (PMID 35773720, 2022). "The role of FOXP3 in regulating the suppressive function of human Tregs is exemplified by loss-of-function FOXP3 mutations, which result in primary Treg dysfunction and effector T cell (Teff) abnormalities, leading to the monogenic autoimmune disease, IPEX syndrome." (PMID 34737751, 2021). "In addition to causing autoimmune diseases, Foxp3 dysregulation could also result in typical allergic inflammation in humans from infancy through to adulthood." (PMID 34239942, 2021). "Also, in other autoimmune diseases gene polymorphism at Foxp3 locus has been reported." (PMID 33519807, 2020). "Foxp3 gene polymorphisms in promoter region could affect the function and quantity of Foxp3 molecule, which results in defects in Treg function, have been associated with various autoimmune disease and clearance of viral infections." (PMID 28298239, 2017). "Polymorphisms of FOXP3 gene promoter may change the binding specificity of transcription factors and are related to initiating transcription, therefore, may affect the function or quantity of Treg, resulting in various autoimmune diseases." (PMID 28298239, 2017). "These disturbances could be elucidated by the fact that, by preventing the activation of autoreactive pathogenic cells, CD4+CD25+FOXP3+ regulatory T lymphocytes (Tregs) have a critical role in the maintenance of self-tolerance and thus in the prevention of autoimmune disease." (PMID 25653477, 2015). "Specifically, the Foxp3-mediated induction of Treg cells may control autoimmune diseases by eliminating inflammation caused by effector T cells; thus Baicalin might serve as a promising natural immunosuppressive compound for the treatment of autoimmune diseases." (PMID 22591709, 2012). "Foxp3 is a pivotal transcription factor for regulatory T cells, which help suppress excessive immune responses and prevent autoimmune diseases." (PMID 41269996, 2025). "Tumors can prompt CD4+ T cells to transform into CD4+CD25+FOXP3+ Treg cells, crucial in the progression of autoimmune diseases and tumors." (PMID 41438510, 2025). "Contrary to adults, Foxp3 degradation in neonates led to severe autoimmune disease featuring pronounced T cell activation, myeloproliferation, and tissue inflammation similar to those in Foxp3-deficient Foxp3GFPKO mice indicative of a loss of Treg function." (PMID 41062655, 2025). "CD4+CD25+FoxP3+ Tregs are essential for maintaining peripheral tolerance, and their depletion leads to spontaneous autoimmune disease in both mice and humans." (PMID 40852720, 2025). "IL-35 is an anti-inflammatory cytokine that is believed to be produced by Tregs, which can inhibit autoimmune diseases, improve immune tolerance by inducing Treg proliferation, inhibit Th1/Th17 cells, and upregulate Foxp3+Treg-related responses." (PMID 40075055, 2025). "Given the prominent role of CD4+FOXP3+ T regulatory cells in autoimmune disease, it is relevant to discuss the modulatory roles of B lymphocytes in inverse vaccination." (PMID 40710338, 2025). "By investigating the modulation of the Treg/Th17 balance and the regulation of Foxp3 methylation through DNMT1, we hope to clarify the underlying mechanisms of TCM in autoimmune diseases and provide potential targets for therapeutic intervention." (PMID 40918088, 2025).
autoimmune disease (continued). "The Treg-modulating factor BACH2 is indispensable for the inhibition of lethal inflammation, and a correlation between BACH2 and FoxP3 levels was identified in multiple sclerosis and Hashimoto’s thyroiditis, both autoimmune diseases." (PMID 41462398, 2025). "Autoantigen−specific CD4+ T cells are central to the development of autoimmune diseases, while the expansion of regulatory T (Treg) cells expressing Forkhead box protein 3 (Foxp3) is essential for mitigating these conditions." (PMID 40702356, 2025). "Despite the development of severe autoimmune disease, we observed an increase in both the absolute number and percentage of FOXP3+ Treg cells in the lymph nodes." (PMID 40183773, 2025). "Despite numerous studies examining the Treg/Th17 ratio in various autoimmune diseases as an indicator of inflammatory status, limited research has explored the impact of parasitic antigens on altering the FOXP3/RORɣt expression ratio." (PMID 40701996, 2025). "Immune profiling in POI that shows diminished FOXP3+ regulatory T-cell tone and Th17 skewing is compatible with inherited tolerance fragility and aligns with the frequent coexistence of other autoimmune diseases or APS." (PMID 41465179, 2025). "Dysregulation or deficiency in Treg function, often due to mutations in the FOXP3 gene as seen in disorders like IPEX syndrome, leads to autoimmune diseases characterized by unchecked immune activation against self-antigens." (PMID 39372653, 2024). "Previous studies have shown that factors like retinoic acid and histone deacetylase inhibitors can induce or stabilize Foxp3 expression, promoting iTreg differentiation in vivo and treating autoimmune diseases." (PMID 38291338, 2024). "Treg dysfunction is linked to several autoimmune disorders, including type 1 diabetes, rheumatoid arthritis, and systemic lupus erythematosus (SLE), with mutations in the Treg transcription factor FOXP3 further driving autoimmune disease development." (PMID 39669275, 2024). "In our review, we addressed the functional distinctions between Foxp3+Tregs and other T cells, highlighting their roles in autoimmune diseases and cancer." (PMID 39290699, 2024). "CD4+CD25+forkhead box P3 (Foxp3)+ Tregs have potent immunosuppressive functions and contribute to immune tolerance maintenance and the control of autoimmune disease development." (PMID 39606248, 2024). "Regulatory T lymphocytes expressing the transcription factor Foxp3 (Tregs) play an important role in the prevention of autoimmune diseases and other immunopathologies." (PMID 38404576, 2024). "STAT1 overexpression and GATA3 overexpression in FOXP3+ Tregs have been reported in autoimmune diseases." (PMID 38774869, 2024). "The expression of FOXP3 ensures that Tregs can effectively modulate immune responses, preventing autoimmune diseases and maintaining immune system homeostasis." (PMID 38398067, 2024). "We designed a custom T cell panel to detect CD3ε, CD4, CD8α and FoxP3 in murine tissue to characterize T cell infiltrates in murine syngeneic tumors and autoimmune disease models." (PMID 38605049, 2024). "Regulatory T cells, an inhibitory T lymphocyte subset characterized by the transcription factor Foxp3, plays a critical role in modulating the immune response to self and foreign antigens and helping to prevent autoimmune disease like MS and EAE." (PMID 38835441, 2024). "Simultaneous deletion of these enzymes results in the generation of a range of autoantibodies, underscoring their pivotal role as key regulators involved in Foxp3 histone acetylation for preventing life-threatening autoimmune diseases." (PMID 39144146, 2024). "This study underscored the potential for targeted therapeutic strategies, such as enhancing Treg activity to restore balance in autoimmune diseases or depleting Foxp3+Tregs to augment anti-tumor immune responses in cancer." (PMID 39290699, 2024).
autoimmune disease (continued). "The disruption of FOXP3 function, either genetically or pharmacologically, leads to severe autoimmune diseases that result in early mortality unless the patient receives a bone marrow transplant." (PMID 39062908, 2024). "They express CD4 and the transcription factor forkhead box protein P3 (FoxP3) and play a crucial role in maintaining immune homeostasis by regulating peripheral tolerance and suppressing autoimmune diseases through diverse immunosuppressive mechanisms." (PMID 38894865, 2024). "FOXP3+ regulatory T cells have become therapeutic targets in preventing autoimmune diseases, preventing transplant rejection and inhibiting the progression of tumors, as they have an active mechanism in immune suppression." (PMID 39770446, 2024). "In certain autoimmune diseases like type 1 diabetes, multiple sclerosis, autoimmune hepatitis, and Sjogren syndrome, there is an increased frequency of IFNγ+Foxp3+ thymic Treg cells in the peripheral blood." (PMID 38259494, 2023). "Expansion of CD4+ Foxp3+ Treg cells in the peripheral blood has been reported in patients with autoimmune diseases after intravenous administration of high-dose (1~2 g/Kg of body weight) heterologous IVIg." (PMID 38094290, 2023). "Disruption of FOXP3 leads to early onset of multi-organ inflammation and fatal autoimmune disease in mice and men." (PMID 36562079, 2023). "Functional mutations or polymorphisms affecting forkhead box P3 (FOXP3) can lead to their abnormal FOXP3 gene expression and/or defective Treg cells generation, thus resulting in autoimmune disease and inflammatory disorders." (PMID 36717877, 2023). "For example, mutations in the Treg transcription factor, Forkhead box P3 (FOXP3), can drive the development of autoimmune diseases in multiple organs within the body." (PMID 36675037, 2023). "Quantitation of the impact of Tregs on tumor growth has been difficult in the past due to the fact that mice lacking Tregs die within 3-4 weeks of birth and methods to systemically deplete FOXP3+ cells from mature mice have led to serious autoimmune disorders." (PMID 37928524, 2023). "We therefore examined the relationship between Foxp3 and Helios expression in a heterogeneous group of patients with inflammatory and autoimmune diseases." (PMID 37350974, 2023). "Genetic ablation of OGT in Foxp3+ cells decreases Treg cell lineage stability, which can eventually elevate the severity of autoimmune diseases." (PMID 37936703, 2023). "The balance of FOXP3 splicing isoforms is related to autoimmune diseases, inflammatory diseases, and cancers." (PMID 37868998, 2023). "Intravenous administration of polyvalent human IgG induced significant expansions of CD4+ Foxp3+ Treg cells and clinical improvements in patients with autoimmune diseases." (PMID 38094290, 2023). "Polymorphisms in various regions of FOXP3 gene including the promoter, intron and exon region, may change its role functionally or quantitatively, and thus give rise to the dysfunction of Tregs, resulting in some chronic inflammation and certain autoimmune diseases." (PMID 36717877, 2023). "Regulatory T cells CD4+FOXP3+ (Tregs) control the immune response to autoantigens and play a key role in the development of autoimmune diseases." (PMID 38201281, 2023). "FOXP3+ regulatory T cells (Treg) are indispensable for immune homoeostasis and for the prevention of autoimmune diseases." (PMID 37741949, 2023). "Application of IL-2 neutralizing antibody to CD25 can reduce the number of Foxp3+ Treg cells and the expression of Foxp3 in individual cell, and even induce the occurrence of autoimmune diseases." (PMID 38129374, 2023). "Pathogenic FOXP3 variants cause immune dysregulation polyendocrinopathy enteropathy X-linked (IPEX) syndrome, a progressive autoimmune disease resulting from disruption of the regulatory T cell (Treg) compartment." (PMID 36600150, 2023).